LRRIQ1 (leucine rich repeats and IQ motif containing 1)
Synonyms: KIAA1801; FLJ12303
Tractability: No criterion of Open Targets' tractability assessment is met for any kind of drug.
Gene: Protein-coding gene on chromosome 12 (85,036,314 to 85,264,457, forward strand). Ensembl gene ENSG00000133640.
Gene Ontology:
Biological process: regulation of signal transduction
Cellular component: microtubule cytoskeleton
Genetic constraint (gnomAD): Loss-of-function variants: 116 observed, 118.69 expected, observed/expected ratio (o/e) 0.98, 90% interval 0.84 to 1.14. The upper end of that interval is the gene's LOEUF score, 1.14, which puts it in group 4 of 6, group 1 being the genes least tolerant of losing a copy. Missense variants: 1,507 observed, 1,365.8 expected, observed/expected ratio (o/e) 1.1, 90% interval 1.06 to 1.15. Synonymous variants: 499 observed, 467.25 expected, observed/expected ratio (o/e) 1.07, 90% interval 0.99 to 1.15.
Homologues: Orthologues: chimpanzee LRRIQ1 (99% identical), macaque LRRIQ1 (89% identical), dog LRRIQ1 (72% identical), pig LRRIQ1 (69% identical), rabbit LRRIQ1 (67% identical), mouse Lrriq1 (58% identical).